RNF180 (ring finger protein 180)
Diseases named in the same sentence as RNF180 in open-access papers (continued):
Sharing a sentence is not in itself a finding about the gene and the disease.
tumor (continued). "We also observed that the performance of RNF180 and SFRP2 combined with traditional tumor markers to predict GC (AUC=0.858) was slightly better than that of the combination of the RNF180 and SFRP2 alone (AUC=0.844)." (PMID 39541711, 2024). "When comparing the effects of RNF180 and SFRP2 with traditional tumor markers (CEA, CA125, and CA199), significant differences were found between the GC and healthy individual groups for all five genes." (PMID 39541711, 2024). "The results showed that the combined detection of RNF180 and SFRP2 genes outperformed traditional tumor markers in GC diagnosis, with a sensitivity of 85.4 % and specificity of 76.9 %." (PMID 39541711, 2024). "The results show that KRT8, PSMD2, TRIM28, and UBE2V2 are significantly overexpressed in tumor tissues, while the expression level of FBXO9, MYLIP, and RNF180 is significantly reduced in LUAD (p < 0.05)." (PMID 35711913, 2022). "Beyond uncovering tumor suppressive functions of RNF180 and its mechanism of regulation on WISP1, our findings have presented a novel therapeutic strategy to restore RNF180/WISP1 pathway for CRC treatment." (PMID 33553163, 2020). "Mechanistically, RNF180 ubiquitinated WISP1, resulting in WISP1 downregulation and ultimately leading to suppression of CRC tumor growth in patient-derived xenograft (PDX) mouse models." (PMID 33553163, 2020). "RKO cells stably expressing RNF180, WISP1, or both were injected subcutaneously into nude mice (n = 6 per group) and tumor development was evaluated." (PMID 33553163, 2020). "Our study revealed that RNF180 co-localized with WISP1 and subsequently ubiquitinated WISP1, targeting it for degradation, to execute tumor suppressive effects in CRC." (PMID 33553163, 2020). "Immunohistochemistry (IHC) staining of RNF180 in CRC tissues was carried out, and tumor samples were characterized as RNF180 low or RNF180 high groups for further analyses." (PMID 33553163, 2020). "Second, RNF180 induction led to WISP1 ubiquitination, resulting in suppression of tumor growth both in vitro and in vivo." (PMID 33553163, 2020). "The last two predictors of the FCC were linked to the DNTY gene, which has no known function, and the RNF180 gene which has been identified as a tumour suppressor." (PMID 39695947, 2024). "In this study, we selected RNF180 and SFRP2 genes from GC patients, patients with precancerous gastric lesions, and healthy individuals, and compared and co-analyzed them with conventional tumor markers (CEA, CA199, and CA125)." (PMID 39541711, 2024). "Therefore, we explored the sensitivity and specificity of combining RNF180 and SFRP2 with traditional tumor markers for detecting GC." (PMID 39541711, 2024). "Notably, when cells were transduced with both WISP1 and RNF180, RNF180 expression reversed the effects of WISP1 on promoting tumor growth." (PMID 33553163, 2020). "As a tumor suppressor gene, RNF180 also has a certain expression level in the cells of the normal body, and its expression also has important physiological functions." (PMID 33082325, 2020). "In tumor specimens, the RNF180 mRNA levels were significantly lower than those in non-tumor specimens (P = 0.003)." (PMID 27050149, 2016). "In addition, we found an obvious negative correlation between RNF180 protein expression in tumor tissues and lymph node metastasis stage in patients with GC3." (PMID 33082325, 2020). "We measured the expression of RNF180 in 113 pairs of tumor and adjacent non-tumor tissues by IHC." (PMID 33082325, 2020). "Consistent with tumor growth results, TUNEL staining showed dramatically increased apoptotic cells in mice with RNF180 overexpression, whereas no significant apoptosis alteration was observed in RNF180+WISP1 mice compared to control mice." (PMID 33553163, 2020).
cancer (10 papers, 2014 to 2025). A tumor composed of atypical neoplastic, often pleomorphic cells that invade other tissues. "The expression of RNF180 was remarkably lower in various cancers (p < 0.05 in all projects except SKCM)." (PMID 33553163, 2020). "The transcriptional levels of RNF180 (mRNA) in the four cancer cell lines considerably increased compared with those in the MGC-803-vehicle cell line." (PMID 27223257, 2016). "Subsequently, four MGC-803 cancer cell lines were transfected with the four RNF180 DNA promoter fragments with demethylated CpG islands." (PMID 27223257, 2016). "Thus, RNF180/WISP1 pathway intervention represents an attractive avenue for exploring future cancer therapies." (PMID 33553163, 2020). "RNF180 has been shown to play key contributions to the development of several types of cancers." (PMID 33553163, 2020). "RNF180 participates in tumorigenesis and likely suppresses the progression of human cancers." (PMID 27223257, 2016). "Thus, RNF180 may have a broader role and potential as a therapeutic target for cancer treatment." (PMID 33553163, 2020). "However, whether RNF180 could also be involved in other cancers remains to be determined." (PMID 33553163, 2020). "The colony formation and MTT assay results suggested that the methylation of CpG islands of RNF180 promoter was capable of enhancing the proliferation and viability of MGC-803 cancer cells." (PMID 27223257, 2016). "The flow cytometry assay results suggested that the methylation of CpG islands (CpG+97 and CpG+102) of the RNF180 promoter could enhance cell synthesis and improve the mitosis of MGC-803 cancer cells." (PMID 27223257, 2016).
RNF180 also shares sentences with these, for which no sentence is quoted: stomach cancer (3 papers); cardiomyopathy (1); colon cancer (1); diabetes (1); esophageal cancer (1); gastric diseases (1); non-small cell lung carcinoma (1); tobacco use disorder (1).